G6PD (glucose-6-phosphate dehydrogenase)
Diseases named in the same sentence as G6PD in open-access papers (continued):
Sharing a sentence is not in itself a finding about the gene and the disease.
cancer (continued). "Total proteomics analysis revealed a significant increase in the abundance of two key enzymes in the oxidative branch of pentose phosphate pathway (PPP), glucose-6-phosphate dehydrogenase (G6PD) and 6-phosphogluconate dehydrogenase (6PGD) in cancer cells exposed to FAK-depleted CAF CM." (PMID 32157087, 2020). "Disregarding the reticular part of PPP and focusing only on G6PD function might hamper our comprehension of PPP role in cancer cell biology." (PMID 33335166, 2020). "The hyper-expression of G6PD is frequent in cancer cells and could be considered a biomarker of poor prognosis, indicating that G6PD has a fundamental role in tumorigenesis." (PMID 32528879, 2020). "DHEA has been widely used as a G6PD inhibitor to suppress the PPP in cancer cells." (PMID 31500396, 2019). "Novel methods of inhibiting the action of G6PD through modulating the metabolic switch, redox homeostasis, and protein–protein interactions are of great interest in thwarting rapid growth, metastasis, and heterogeneity of cancer cells." (PMID 31500396, 2019). "Exploiting G6PD as a potential drug target against cancer is also discussed." (PMID 31500396, 2019). "G6PD activity influenced lapatinib effect on cancer cells by preventing autophagy; iii." (PMID 30987650, 2019). "Since G6PD is a biomarker and G6PD inhibition has potential as a therapy for cancer, a promising series of recently developed inhibitors could be designed according to their interaction." (PMID 31500396, 2019). "Indeed, targeting G6PD results in cancer cytotoxicity, reduction of metastases and restoration of sensitivity to drug." (PMID 30987650, 2019). "Activation of G6PD is the first line response against oxidative stress in cancer cells." (PMID 31500396, 2019). "For example, induction in the expression and activity of the metabolic oncogene G6PD by 1,25(OH)2D3 may enhance cancer cells’ survival, due to the generated NADPH, which could be used for reductive biosynthesis and anti-oxidant defense." (PMID 30181873, 2018). "G6PD inhibition has been previously shown to limit cancer cell survival." (PMID 30181873, 2018). "Some studies have found that G6PD presented high activities in some cancers, while others put forward the hypothesis of a lower cancer incidence in G6PD deficient subjects." (PMID 29445340, 2018). "This may explain why G6PD upregulation is correlated with cancer progression through the upregulation of β-catenin signaling." (PMID 29317613, 2018). "Therefore, we performed a G6PD enzyme activity assay on carcinoma protein lysates, as well as on purified G6PD." (PMID 29760380, 2018). "Importantly, we further demonstrate that Plk1-mediated activation of G6PD is critical for its role to promote cell cycle progression and cancer cell growth." (PMID 29138396, 2017). "G6PD is thus a target for cancer treatment being addressed by many groups around the world." (PMID 29955429, 2017). "Lately, increasing evidences show that high expression of G6PD predicts poor overall survival of patients with numbers of cancers, indicating that G6PD may play important roles in tumorigenesis." (PMID 29312589, 2017). "In addition to the so-called Warburg effect, G6PD was aberrantly activated in order to generate sufficient building blocks required for rapid proliferation and adaptation of cancer cells to the altered internal and external environment." (PMID 29312589, 2017). "NADPH, sourced from G6PD fuels nucleotide biosynthesis, maintains redox potential of thioredoxin and glutathione and drives the mevalonate pathway that powers many of the basic mechanisms by which cancer cells escape host control." (PMID 29955429, 2017). "However, the question why G6PD is highly expressed and exhibits aberrant activities in a number of human cancers is far from being answered." (PMID 29312589, 2017). "Surprisingly, G6PD and VEGF crosstalk in cancer cells and are highly associated with angiogenesis." (PMID 29158891, 2017).
cancer (continued). "Here, by defining the essential role of G6PD activation in Plk1-mediated cell cycle control and cancer progression, our results reinforced the importance of crosstalk between cell mitosis and metabolic changes and, in particular, the significance of metabolic inputs in determining the cell fate." (PMID 29138396, 2017). "Furthermore, G6PD glycosylation was shown to promote cancer cell proliferation in vitro and tumor growth in vivo." (PMID 28553614, 2017). "The idea arose that inhibition of the one (G6PD) and strenghtening of the other (Par-4) could be helpful in cancer therapy." (PMID 27872579, 2016). "Our findings that O-GlcNAcylation positively regulates G6PD activity add a new mechanistic insight into the regulation of PPP, and suggest that modulating G6PD activity may represent a potential therapeutic strategy for cancer." (PMID 26399441, 2015). "In addition, glycosylation of G6PD promotes cancer cell proliferation in vitro and tumor growth in vivo." (PMID 26399441, 2015). "In addition, G6PD also promotes cancer survival by producing NADPH, a key tool for tumor cells to defend against oxidative stress, chemotherapy-induced cytotoxic damage, as well as for promoting biosynthesis." (PMID 24738035, 2014). "Thus, rapidly proliferating cells or cancer cells usually increase the PPP flux by activating G6PD to meet the bioenergetic demands during proliferation." (PMID 25015087, 2014). "Therefore, elevated and active PPP enzymes, for instance, TKTL or G6PD, are frequently observed in malignant, aggressive, proliferative and drug-resistant cancer cells." (PMID 24738035, 2014). "Upregulation of key PPP enzymes such as G6PD increases cancer cell proliferation in vitro." (PMID 25250177, 2014). "Furthermore, increased expression of G6PD has been documented in cancers of the lung, breast, colon, prostate, cervix, and endometrium." (PMID 22848499, 2012). "In addition, there is research on the role of G6PD in cancer cell metabolism." (PMID 39259139, 2024). "Therefore, serine-mediated one-carbon metabolism compensates for G6PD loss in KL cancer cell survival, although this does not preclude the potential compensatory cytosolic NADPH production through ME1 or IDH1." (PMID 38997257, 2024). "Thus, G6PD may mediate, at least in part, the regulation of the senescence phenotype of cancer cells by TAp73." (PMID 37680899, 2023). "However, G6PD-mediated carcinogenic effects are dispensable in KRAS-mutant cancer cells." (PMID 36755301, 2023). "Additionally, trametinib is also recommended by BRAF and MAP2K1 alterations, as well as new molecular evidence, such as G6PD (mutation and high overexpression), CDKN2A (deletion and underexpression) and due to the genetic dependency of MAP2K1 in BRAF-mutant cancer cell lines." (PMID 37207338, 2023). "Furthermore, studies have shown that G6PD is intimately related to the occurrence and development of tumors and critical for signaling pathways that control cell proliferation and cell death in rapidly growing cancer cells." (PMID 37601657, 2023). "However, the GLUT protein family responsible for glucose transport and several key enzymes behind glucose metabolism, such as phosphofructokinase (PFKL) and glucose-6-phosphate dehydrogenase (G6PD), is abnormally overexpressed in some specific cancer varieties." (PMID 38139250, 2023). "G6PD could promote cancer progression through its effects on some metabolic pathways." (PMID 38098504, 2023). "Therefore, RRX-001 as an inhibitor of G6PD for cancer treatment is particularly promising." (PMID 35207558, 2022). "Moreover, RRx-001 may interfere with redox homeostasis in cancer cells by downregulating G6PD expression." (PMID 35601559, 2022). "Therefore, aiming to target G6PD may be a potential way to treat cancer, particularly in cases with high G6PD expression." (PMID 35207558, 2022).
cancer (continued). "Taking into account that G6PD essentially contributes to cancer cell multiplication, metastasis and survival, the development of potent and particular G6PD inhibitors might open up new avenues for cancer therapy." (PMID 35991850, 2022). "Thus, the inhibition of G6PD has emerged as a potential therapeutic strategy for treating cancer." (PMID 35207558, 2022). "Therefore, enhanced G6PD activity maybe induce the resistance of cancer cells to chemotherapeutic drugs." (PMID 35207558, 2022). "The enzyme glucose-6-phosphate dehydrogenase (G6PD) is involved in the maintenance of redox homeostasis as a catalytic enzyme of the oxidative pentose phosphate pathway and may be a therapeutic target for cancers." (PMID 36225575, 2022). "Studying the regulation of G6PD by RIP140 in other types of cancers could also be of interest." (PMID 35806424, 2022). "In addition, this suggests that the inhibition of PPP or G6PD in combination with DNA damage inducing chemotherapies, such as 5-fluorouracil (5-FU) and doxorubicin, may restore chemosensitivity in cancer cells." (PMID 33834022, 2021). "Therefore, we hypothesized that G6PD might play a role in modulating lapatinib effect on cancer cells." (PMID 30987650, 2019). "Moreover, to confirm the metabolic effects of pioglitazone we investigated key proteins indicative of altered glucose metabolism in cancer cells, such as the transporters Glut-1 and SLC15A (Solute-linked carrier family A1 member 5), G6PD (glucose-6-phosphate dehydrogenase) and TKTL1 (Transketolase)." (PMID 31027492, 2019). "Based on this, we hypothesised that G6PD blockade could increase Lapatinib effect on cancer." (PMID 30987650, 2019). "In addition, several studies have demonstrated that c-Myc promotes both glutamine uptake and the catabolic process of glutamine.The activity of glucose-6-phosphate dehydrogenase (G6PD), a critical enzyme participating in the pentose phosphate pathway, was reported to be increased in cancer cells." (PMID 30532734, 2018). "A previous study suggested that G6PD inhibitor 6-AN sensitized various cancer cells to cisplatin through increasing cisplatin accumulation and Pt-DNA adduct formation, but whether the inhibition of G6PD sensitized cisplatin via regulating the PPP activity and redox homeostasis remained unclear." (PMID 29445340, 2018). "However, more work is needed in order to find lead G6PD inhibitors as candidate anti-cancer drugs." (PMID 24342878, 2013). "Similar to cancer cells, the concentration of ROS was significantly increased in lal−/− bone marrow MDSCs, which was accompanied by up-regulation of nitric oxide/ROS production genes, glutathione peroxidase/glutathione reductase genes, and glucose 6-phosphate dehydrogenase gene." (PMID 22383970, 2012). "ME1, G6PD, and IDH1 all play important roles in metabolic pathways that are often altered in cancer cells to support their rapid growth and proliferation." (PMID 39996805, 2025). "Up-regulation of G6PD, the first and rate-limiting enzyme of the PPP, occurs in multiple cancers and increases NADPH production capacity, thereby playing a central role in protecting cells from ROS." (PMID 40802750, 2025). "Among the overlapping upregulating genes are G6PD and KLF4, known to be related to cisplatin resistance and upregulated in lung and other cancers." (PMID 41469472, 2025). "Through systematic experiments, we demonstrated that hypoxia significantly upregulates G6PD expression in HCC cells and that G6PD is essential for maintaining cancer stemness." (PMID 41050691, 2025). "Firstly, G6PD acts as the rate-limiting enzyme in the Pentose Phosphate Pathway (PPP), one of two crucial pathways, along with aerobic glycolysis, for cancer cell proliferation." (PMID 41374996, 2025).
cancer (continued). "Essential targets in therapeutic targeting of cancer metabolism are glycolytic enzymes, including LDHA, PKM2, HK2, ALDOA, G6PD, PPP cycle, glutamine serine metabolism and pyruvate oxidation." (PMID 40076506, 2025). "Upregulation of G6PD has been reported to increase therapy- and drug-resistance as well as AKT signaling in cancer cells." (PMID 39819475, 2025). "In contrast, glucose-6-phosphate dehydrogenase (G6PD), a key enzyme in the PPP, supports cancer cell survival by blocking ferroptosis." (PMID 41462004, 2025). "The pentose phosphate pathway, along with its rate-limiting enzyme, glucose-6-phosphate dehydrogenase, is essential for both the antioxidative response and the synthesis of ribonucleotides and may play a critical role in the proliferation and growth of cancer cells." (PMID 39796677, 2024). "Further understanding the regulation and function of G6PD in various cancers may offer new insights into therapeutic strategies aimed at targeting metabolic vulnerabilities and overcoming resistance to ferroptosis, potentially leading to more effective cancer treatments." (PMID 39534872, 2024). "G6PD, a pivotal enzyme of the PPP, exhibits aberrant overexpression in diverse chemoresistant cancer cells, including ovarian and NSCLC, and confers resistance to oxidative stress and increased viability." (PMID 38351531, 2024). "G6PD performs an important part in tumor growth, PPP and oxidative stress and is a key factor in regulating metabolic reprogramming of cancer cells." (PMID 39516455, 2024). "These miRNAs inhibit TKDT and G6PD genes, and their repression by histone deacetylase 4 (HDAC4) through NRF2 supports cancer cell growth." (PMID 38247494, 2024). "Concurrently, in cancer cells with high NADPH consumption, the activity of G6PD is significantly enhanced to compensate for NADPH depletion." (PMID 38739940, 2024). "G6PD and PDK1 are known to regulate the Warburg Effect, a phenomenon in which cancer cells preferentially use glycolysis for energy production." (PMID 38351531, 2024). "This resistance to ferroptosis is particularly evident in clear cell renal cell carcinoma and HCC, where elevated G6PD expression and PPP activation have been shown to protect against oxidative damage and promote cancer cell survival." (PMID 39534872, 2024). "We, for the first time, show that the tumor metabolic microenvironment lactic acid activates a “signalosome” comprising GSTP1, SRC and G6PD by attenuating the complex, which facilitates a reprogrammed PPP to promote cancer cell growth." (PMID 37491277, 2023). "HSP27-knockdown cancer cells exhibit higher levels of mitochondrial and cellular ROS, as well as decreased levels of GSH and G6PD." (PMID 37628819, 2023). "Intriguingly, TRIM21 negatively regulates glucose metabolism in human cancers by modulating the degradation of regulators to promote the dysregulation of glycolysis, for example, promoting the degradation of PFKP and G6PD." (PMID 38092733, 2023). "HSP27-knockdown cancer cells exhibited decreased levels of reduced glutathione (GSH) and glucose6phosphate dehydrogenase (G6PD), a crucial pentose phosphate pathway enzyme." (PMID 37628819, 2023). "The expression of LPCAT1, NDRG1, G6PD, CYP7A1, SPP1, SFN, and CDCA8 was significantly higher in cancer tissues than in paraneoplastic tissues, whereas the expression of DNASE1L3 was significantly lower in cancer tissues." (PMID 37717019, 2023). "G6PD, the first and rate-limiting enzyme of the PPP oxidative phase, is upregulated in several cancer types." (PMID 37190196, 2023). "The key rate-limiting enzyme of the PPP oxidative arm is the glucose-6-phosphate dehydrogenase (G6PDH), which has been reported to be activated or overexpressed in several cancers." (PMID 38132097, 2023). "Meanwhile, six commonly used anti-cancer drugs including 5-fluorouracil, Etoposide, Imatinib, Methotrexate, and Tamoxifen had higher IC50 values in patients with higher G6PD expression levels." (PMID 37601657, 2023).
cancer (continued). "And G6PD expression is increased in the infiltration levels of B cells, CD8+ T cells, CD4+ T cells, macrophages, neutrophils, and dendritic cells in many cancers, especially in KIRC, LGG, and LIHC." (PMID 37601657, 2023). "In both paired and unpaired samples of HCC patients, EZH2, G6PD, LGALS3 and PSMD14 were highly expressed in the cancer and lowly expressed in the paracancer, with statistically significant differences." (PMID 37853322, 2023). "Thus, targeting G6PD with different approaches could pave the way for novel cancer therapies." (PMID 38139067, 2023). "Recent evidence showed that both the glucose-6-phosphate dehydrogenase (G6PD) pathway and a less characterized hexose-6-phosphate dehydrogenase (H6PD) pathway contribute to accelerated cancer cell growth." (PMID 35163973, 2022). "After treatment of NSCLC cells with lactate, the degree of Kla and HIF-1α increases and the transcription of HK-1, glucose 6-phosphate dehydrogenase (G6PD), and PKM decreases, which jointly regulates the metabolism of cancer cells." (PMID 35757394, 2022). "ALKBH5 regulates FOXM1, G6PD, SOX2, and AKT2 expression in an m6A-dependent manner to promote cancer cell proliferation, invasion and drug resistance." (PMID 35945641, 2022). "ALKBH5 promotes cancer progression by regulating TIMP3, FOXM1, CDKN1A, JAK2, FOXM1, AURKB, G6PD, HBx, USP1, NANOG, PVT1, IGF1R lncRNA NEAT1, and lncRNA RMRP expression." (PMID 35945641, 2022). "G6PD as the first and rate-limiting enzyme of PPP also plays an important role in the development of cancer." (PMID 35207558, 2022). "Nevertheless, similarly to G6PD, PFK1 and PKM2, PGK1 O-GlcNAcylation favors cancer cell proliferation and promotes tumorigenesis." (PMID 36359905, 2022). "Glucose-6-phosphate dehydrogenase (G6PD), which converts G6P to 6-phosphogluconate (6-PG), is the key regulatory enzyme for PPP and is upregulated in most cancers." (PMID 36618350, 2022). "Moreover, it has been well confirmed that G6PD was involved in certain carcinogenesis, and served key roles in extensive cancer cell metabolic reprogramming, including affection the amino acid metabolic pool 43-45, which may in turn provide building blocks for MMP9 protein synthesis." (PMID 34975298, 2022). "Inhibition of G6PD is primarily responsible for the inhibition of skin tumor promotion by DHEA and structural analogs and very likely contributes to its cancer preventive and anti-atherosclerotic action in other experimental models." (PMID 35371612, 2022). "The competitive G6PD inhibitor 6-AN and uncompetitive G6PD inhibitor DHEA have been widely used in various cancer studies." (PMID 35207558, 2022). "We also found a correlation between G6PD expression and the PI3K/AKT signalling pathway in cancer, the PPARα pathway, glycolysis, and gluconeogenesis, suggesting a correlation with tumour proliferation." (PMID 35712981, 2022). "PPP suppression has been used in cancer therapy apart from glycolysis, and the enzymes symbolic for the non-oxidative or oxidative phase of PPP are transketolase (TKT) and glucose-6-phosphate dehydrogenase, respectively." (PMID 36158697, 2022). "G6PD has been considered the pacesetter for NADPH production and is overexpressed in various cancers like hepatocellular carcinoma and breast and lung cancer." (PMID 36013278, 2022). "G6PD is the main contributor of NADPH (from NADP+) in proliferating cells through the Pentose Phosphate Pathway and G6PD targeting leads to reduced NADPH and impaired cell growth in several cancer models." (PMID 34887471, 2021).